EIF4A1 (eukaryotic translation initiation factor 4A1)
Diseases named in the same sentence as EIF4A1 in open-access papers (continued):
Sharing a sentence is not in itself a finding about the gene and the disease.
tumor (continued). "In vivo assay further suggested that AS-IV suppressed tumor growth via targeting circDLST to regulate miR-489-3p and EIF4A1 levels." (PMID 35435117, 2022). "The GSVA score of the gene set negatively correlated with EIF4A1 was lower in the tumor tissues (0.673 vs. 0.787, p < 0.0001)." (PMID 36101357, 2022). "Given the underlying role of EIF4A1 in tumor progression, we compared the expression of EIF4A1 in tumor and paired adjacent tissues, which revealed a significantly increased level of EIF4A1 in ccRCC." (PMID 35592316, 2022). "Simultaneously, GSEA confirmed the pathogenic role of EIF4A1 in LUAD in promoting cell cycle progression and remodeling the tumor immune microenvironment." (PMID 36101357, 2022). "The goals of this study were to explore the functions of circDLST in regulating AS-IV-induced tumor inhibition in GC, as well as its molecular mechanism with miR-489-3p and EIF4A1." (PMID 35435117, 2022). "Among all the genes reported in the literature with their potential cause in tumor development, CPEB4, APC, TRIP13, EIF2S3, EIF4A1, IFNg, PIK3CA and CTNNB1 have particularly been identified to be a set of potential candidates for tumor development." (PMID 33237662, 2021). "Elevated eIF4A1 expression was positively correlated with lymph node infiltration, tumor size, and indicated a poor prognosis." (PMID 34906136, 2021). "Programmed Cell Death 4 (PDCD4) is a tumor suppressor known to bind eIF4A1, which inhibits translation initiation and proliferation." (PMID 22247778, 2012). "Using Programmed Cell Death 4 (PDCD4) EIF4A1 inhibits translation initiation and acts as a tumor suppressor by forming a complex." (PMID 21114830, 2010). "Additionally, eIF4A1 supports the translation of transcription factors involved in immune suppression, facilitating tumor evasion from immune surveillance." (PMID 41299109, 2025). "MYCN-driven high-risk NBs may enhance the eIF4F translation machinery to sustain tumor growth and metastasis, and elevated expression of eIF4A1, eIF4E1, and eIF4G1 correlate with poor prognosis." (PMID 41279557, 2025). "Currently, there is an increasing number of studies of EIF4A1 inhibitors for tumor treatment." (PMID 38918785, 2024). "Furthermore, overexpression of eIF4A1 was significantly correlated with advanced tumor metastasis, epithelial mesenchymal transition, poor tumor differentiation and poor prognosis in GC patients." (PMID 38028556, 2023). "Moreover, TCGA data showed low methylation levels and high gene expression of eIF4A1 in tumor tissue compared to control or paired tissues." (PMID 37409430, 2023). "Taken together, our findings indicate that EIF4A1 may reprogram the tumor immune microenvironment via decreased immunogenicity and immunosuppressive cell recruitment." (PMID 36101357, 2022). "Importantly, the protein level of eIF4A1 is present in similar amounts between BCSCs and non‐BCSCs (bulk tumor cells)." (PMID 33053607, 2022). "Furthermore, EIF4A1 expression increased with the progress of the tumor stage in our cohort of ccRCC tissues." (PMID 35592316, 2022). "Importantly, we found that a high level of eIF4A1 expression was significantly correlated with tumor size and lymph node metastasis." (PMID 34906136, 2021). "Recent studies revealed that eIF4A1 inhibition could significantly repress the tumor growth by remodeling metabolism and DNA replication." (PMID 34906136, 2021). "Additionally, the overexpression of eIF4A1 has been positively associated with advanced tumor-node-metastasis (TNM) stage, poor tumor differentiation, and a poor prognosis in patients with GC." (PMID 34869305, 2021). "Similarly, immunohistochemical staining of the eIF4A1 protein in patients with GC showed that eIF4A1 protein levels are generally increased in tumor tissues." (PMID 34869305, 2021). "Notably, MELK and EIF4A1 were highly expressed in tumor cells." (PMID 40709174, 2025).
tumor (continued). "eIF4A1 is dysregulated and aberrantly expressed in many different tumor tissues, although the exact role of eIF4A1 in tumorigenesis and development is unclear, it may be associated with abnormal RNA unwinds function and lead to aberrant expression of proteins formed by aberrant RNA translation." (PMID 38028556, 2023). "eIF4A1 is often involved as a target of microRNAs or long non-coding RNAs during the epithelial-mesenchymal transition, associating with the proliferation and metastasis of tumor cells." (PMID 38028556, 2023). "The data suggest that higher EIF4A1 expression in a tumor may confer a survival disadvantage." (PMID 36101357, 2022). "We could find the expression of EIF4A1 was elevated as the tumor stage progressed." (PMID 35592316, 2022). "Also, AS-IV recued tumor growth in vivo via targeting circDLST to regulate miR-489-3p/EIF4A1 axis." (PMID 35435117, 2022). "For example, binding of eIF4B to eIF4A1 enhances translation initiation, and we observe an increase of this interaction in DoHH-2 (tumour) relative to GM01953 (non-tumour)." (PMID 39225047, 2024). "In contrast, similarly to what has been described in other tumor types, the treatment of HCC cells with these drugs led to eIF4A2 upregulation, which is considered a compensatory response to marked eIF4A1 suppression." (PMID 36768380, 2023). "In ccRCC, MEXPRESS-based analysis indicated that EIF4A1 levels were related to clinicopathologic features including recurrence after initial treatment, TNM classification, tumor stage, sample type, smoking history, and overall survival." (PMID 35592316, 2022). "So, when eIF4A1 is targeted, both cellular populations will perish at the same time with less chance for MRD and tumor relapse." (PMID 33053607, 2022). "Inhibiting the interactions of PHGDH/eIF4A1 and PHGDH/eIF4E will provide potential targets for anti-tumor therapeutics development." (PMID 30744688, 2019). "Furthermore, it has been reported that outside of serine biosynthesis, PHGDH enhances mRNA translation by interacting with eIF4A1 and eIF4E, thereby promoting PDAC tumor growth." (PMID 38951899, 2024). "Furthermore, EIF4A1 potentiates oncogenesis in LUAD by regulating the cell cycle and by modulating the tumor immune microenvironment." (PMID 36101357, 2022). "We found that the expression of EIF4A1, but not EIF4A2, was higher in tumor tissue and associated with poor clinical outcomes in LUAD patients." (PMID 36101357, 2022). "We found DNA methylation levels to be lower in the tumor tissues and that they had an insignificantly negative correlation (r = −0.14) with EIF4A1." (PMID 36101357, 2022). "Similarly, higher protein levels of EIF4A1 but not EIF4A2 were detected in the tumor tissues of LUAD." (PMID 36101357, 2022). "The expression level of EIF4A1 in tumor tissues was higher than that in normal tissue samples of LUAD, but this was not the case for the expression of EIF4A2, and the expression levels were higher in the advanced stages and advanced lymph node status for EIF4A1 but not EIF4A2 (right two panels)." (PMID 36101357, 2022).
infection (4 papers, 2021 to 2026). The state of being infected such as from the introduction of a foreign agent such as serum, vaccine, antigenic substance or organism. "In addition, perturbation of Hrf-063 or eIF4A1 altered the expression of STAT1 and CAV1, and Hrf-063 regulated ISG15 and STING1 transcription in a time- and infection-dependent manner." (PMID 42306525, 2026).
hematological cancer (1 paper, 2023). "This may be simply attributed to the expression levels of RocA targets (eIF4A1, eIF4A2 and DDX3X), which are much higher in hematological cancer tissues than in normal tissues (data not shown)." (PMID 36725859, 2023).
EIF4A1 also shares sentences with these, for which no sentence is quoted: colon cancer (2 papers); liver cancer (2); thymoma (2); triple-negative breast carcinoma (2); acute respiratory distress syndrome (1); bladder cancer (1); brain tumor (1); breast invasive carcinomas (1); chronic lymphocytic leukemia (1); clear cell renal carcinoma (1); colon adenocarcinoma (1); esophageal carcinoma (1); gallbladder cancer (1); ganglioneuroblastoma (1); head and neck squamous cell carcinoma (1); HIV-1 infection (1); idiopathic cardiomyopathy (1); intrahepatic cholangiocarcinoma (1); ischemic cardiomyopathy (1); malignant glioma (1); medulloblastoma (1); myocardial ischemia (1); nerve sheath tumors (1); non-small cell lung carcinoma (1); osteoarthritis (1); pancreatic ductal adenocarcinoma (1); pilocytic astrocytoma (1); psychiatric diseases (1); testicular germ cell tumor (1); thrombotic microangiopathy (1).